CPT1A (carnitine palmitoyltransferase 1A)
Diseases named in the same sentence as CPT1A in open-access papers (continued):
Sharing a sentence is not in itself a finding about the gene and the disease.
type 2 diabetes (16 papers, 2016 to 2025). "There was nominal evidence for a direct causal association of cg00574958 (CPT1A) with type 2 diabetes." (PMID 37202507, 2023). "Methylation at cg00574958 in CPT1A is associated with type 2 diabetes (T2D), triglyceride levels, and blood pressure." (PMID 34836312, 2021). "Our finding that in Ghanaians, the DMP annotated to gene CPT1A was associated strongly with abdominal obesity suggests the need to explore the role of CPT1A variation in DNA methylation related to increases in WC and increased risk for type 2 diabetes." (PMID 28947923, 2017). "We could not confirm the previously reported nominal and robust associations of CPT1A methylation with type 2 diabetes and fasting glucose in our 2SMR analysis." (PMID 37202507, 2023). "For example, some of our loci, mapping to ABCG1, CPT1A and TXNIP, have been associated with lipid and metabolic traits such as triglycerides, BMI, and type 2 diabetes." (PMID 41361833, 2025). "The replicated associations for type 2 diabetes implicated genes including ABCG1, CPT1A, SREBF1, and TXNIP." (PMID 37410739, 2023). "Genes annotated to CpGs that were associated with type 2 diabetes included ABCA1, ABCG1, CPT1A, SREBF1, SLC7A11, SLC7A5, and TXNIP among others (see S12 Table for full details)." (PMID 37410739, 2023). "The results from our meta-analysis included CpG sites at genes that are known to be associated with type 2 diabetes, such as TXNIP, ABCG1, SREBF1 and CPT1A, showing consistency between cross-sectional and longitudinal studies and also between ethnicities." (PMID 35169870, 2022). "Results from the majority of those studies indicate that differentially methylated sites in the TXNIP, ABCG1, CPT1A and SREBF1 genes are associated with type 2 diabetes and glycaemic traits." (PMID 29164275, 2018). "Similarly, in a murine Type 2 diabetes model, a decrease in cpt1a gene expression decreased lipid synthesis." (PMID 38474201, 2024). "Increased CPT1A expression was reported in PBMC from obese individuals and lymphocytes from patients with type 2 diabetes." (PMID 37280548, 2023). "An EWAS of BMI reported differential methylation at CPT1A and ABCG1, and an EWAS of type 2 diabetes at SREBF1 and ABCG1." (PMID 27350042, 2016). "One of the compounds showing a strong ability to irreversibly inhibit CPT1 (CPT1A and CPT1B), is glycidyl acid derivate etomoxir (ethyl-2-[6-(4-chlorophenoxy)hexyl] oxirane-2-carboxylate), which had been used in the treatment of type 2 diabetes and chronic heart failure." (PMID 35628385, 2022).
renal fibrosis (14 papers, 2021 to 2025). A final common manifestation of a wide variety of chronic kidney diseases characterized by glomerulosclerosis and tubulointerstitial fibrosis. "CNN2 deficiency can upregulate CPT1A and other key enzymes through ESR2-PPARα axis, promote FAO and reduce renal fibrosis after RIRI." (PMID 41451126, 2025). "With conditional overexpression of CPT1A, mitochondrial dysfunction in the fibrosis kidney can be alleviated, and renal fibrosis can be significantly decreased." (PMID 37033619, 2023). "Here, we present that rhein upregulated Cpt1a-mediated FAO through the SirT1/STAT3/Twist1 pathway to improve renal fibrosis." (PMID 35408745, 2022). "The following studies indicated that enhancing FAO hindered renal fibrosis, since CPT1A-knockin mice manifested declined expression of fibrotic markers, reduced inflammatory response, and diminished macrophage influx in renal fibrosis mouse models." (PMID 36467025, 2022). "Our metabolomic study demonstrated that 22 of the 34 differential metabolites between UUO and sham rats were significantly associated with Cpt1a gene, indicating that Cpt1a-mediated FAO plays a very important role in UUO-induced renal fibrosis." (PMID 35408745, 2022). "In this study, we focused on the FAO in renal fibrosis, and we identified metabolic enzymes(CPT1A) and transcription regulators (PGC1α, PPARα) of FAO, which indicated that Hypo-EVs can reverse fatty acid metabolism disorder in fibrotic kidney caused by I/R." (PMID 35526054, 2022). "Collectively, rhein protects rats from renal fibrosis by regulating SirT1/STAT3/Twist1 pathway to promote Cpt1a-mediated fatty acid degradation." (PMID 35408745, 2022). "In this study, we demonstrated that rhein prevents renal fibrosis by promoting Cpt1a-mediated FAO through SirT1/STAT3/Twist1 pathway." (PMID 35408745, 2022). "Overexpression of Cpt1a in RTE cells can protect mice from renal fibrosis by restoring oxidative metabolism and mitochondrial number." (PMID 35408745, 2022). "Indeed, in carnitine palmitoyl-transferase 1A (Cpt1a)-knockin mice overexpression of Cpt1a decreased renal fibrosis, blunted proinflammatory responses, inhibited epithelial cell damage and macrophage infiltration, and prevented mitochondrial dysfunction." (PMID 37440209, 2023). "It was reported that overexpression of Cpt1a can protect mice from renal fibrosis." (PMID 35408745, 2022). "Hypo-EVs suppress the renal fibrosis by restoring CPT1A-mediated mitochondrial FAO, which effects may be achieved through regulation of mitochondrial homeostasis." (PMID 35526054, 2022). "Whether Cpt1a reverses renal fibrosis through its interaction with Twist1 remains to be further studied." (PMID 35408745, 2022). "In summary, our data indicate that Hypo-EVs significantly inhibit the renal fibrosis by restoring CPT1A-mediated FAO, and these effects may be achieved by regulating mitochondrial homeostasis." (PMID 35526054, 2022). "Rhein can improve renal fibrosis by blocking SirT1/STAS3/Twist1/Cpt1a-depandent FAO dysfunction, which may also be one of the mechanisms for rhubarb drugs." (PMID 35408745, 2022). "Decreased expression of Cpt1a and Acox1 prevents the mitochondrial oxidation of fatty acids, which further inhibits the availability of substrates and hinders fatty acid metabolism, and leads to renal fibrosis." (PMID 34987387, 2021). "In three models of renal fibrosis (unilateral ureteral obstruction, folic acid nephropathy, and adenine-induced nephrotoxicity), the extent of renal fibrosis was reduced in CPT1A knockin (CPT1A-KI) mice, and a protective effect against fibrosis was seen following inducing CPT1A overexpression." (PMID 39113692, 2024). "Gain of function in CPT1A strategy may be a novel approach to treating fibrosis in renal fibrosis." (PMID 37033619, 2023). "Therefore, SirT1, STAT3, Twist1 and Cpt1a may represent useful targets for the prevention of renal fibrosis." (PMID 35408745, 2022).
renal fibrosis (continued). "This in vitro model supports the therapeutic potential of CPT1A activation for alleviating EMT and renal fibrosis." (PMID 38308271, 2024). "Further, by overexpressing the Cpt1a gene in 3 models of renal fibrosis, the study identified the therapeutic role of CPT1A, which restores FAO and significantly ameliorates renal fibrosis." (PMID 39737193, 2024). "In renal fibrosis, Twist1 is a driving force of EMT in RTE cells by negatively regulating Cpt1a-mediated FAO." (PMID 35408745, 2022). "Consistent with the reports, our study showed that the gene expression of FAO-related key metabolic enzymes (CPT1A, CPT2, and ACOX2) and the FAO transcription regulatory factors (PPARα and PGC1α) were markedly decreased in renal fibrosis induced by I/R." (PMID 35526054, 2022). "We further assessed fibrotic lesions and found that there was a negative correlation between CPT1A or PPARα expression and renal fibrosis." (PMID 39438470, 2024).
Hypoglycemia (13 papers, 2012 to 2026). A decreased concentration of glucose in the blood. "Patients with CPT1A deficiency often experience multiple morbidities, including hepatic encephalopathy, hypoglycemia, and hyperammonemia." (PMID 40718711, 2025). "The CPT1A p.P479L metabolic variant, also common in Northern Indigenous populations, is associated with hypoglycemia and infant death." (PMID 38884101, 2024). "The prevalence of hypoglycemia in term newborns from the Kivalliq region of Nunavut was 22% in newborns with homozygous p.Pro479Leu variant in CPT1A." (PMID 36109795, 2022). "Every 3 months, the patient was examined by a specialist to evaluate if he suffered any neurological damage due to possible episodes of hypoketotic hypoglycemia that is associated with CPT1A deficiency." (PMID 34233743, 2021). "To date, only two cases of CPT1A deficiency have been reported in China, and both were diagnosed after the patients (> 1 year old) exhibited symptoms of hypoglycemia followed by diarrhea and fever." (PMID 34233743, 2021). "Those with the CPT1A p.P479L variant may be at increased risk for hypoglycemia, especially during illness or prolonged fasting, and beta blocker medication could increase the risk for a hypoglycemic event." (PMID 38884101, 2024). "Not only is the CPT1A variant commonly found among Northern Indigenous populations in Canada and BC First Nations, but hypoglycemia may present with symptoms (e.g., seizures) that can be difficult to differentiate from LQTS." (PMID 38884101, 2024). "These include KCNQ1 p.L353L, a synonymous splice site variant and modifier of the LQTS phenotype, ANK2 p.S646F, a variant associated with structural heart disease and an adult onset form of LQTS, and CPT1A p.P479L, a variant associated with infant death and hypoglycemia." (PMID 38884101, 2024). "Therefore, patients with CPT1A deficiency usually present hypoketotic hypoglycemia and hepatic encephalopathy after long periods of fasting." (PMID 34233743, 2021). "Impaired fatty acid oxidation due to defective CPT1A prevents effective energy production from fats, leading to hypoketotic hypoglycemia; ketogenic diets are therefore contraindicated." (PMID 41486865, 2026). "It is interesting to note that in the experiment aimed at testing the effect of inactivating Cpt1a in AgRPAgpat5KO mice the glucagon response to hypoglycemia was only mildly reduced in the AgRPAgpat5KO mice." (PMID 36180454, 2022). "Although the variant's impact on fatty acid oxidation predisposing children to hypoglycemia is the most likely explanation, the role of CPT1A in the brain has not been well explored; therefore, other mechanisms cannot be excluded at this time." (PMID 38884101, 2024). "Severe CPT1a deficiency, with little or no enzyme activity leads to hypoglycemia, seizures and death if not treated." (PMID 27829488, 2016). "CPT1A deficiency is a rare autosomal recessive disorder, usually presenting in infancy as non-ketotic hypoglycemia and metabolic decompensation triggered by fasting, which can progress to seizures, brain damage, and sudden death." (PMID 23231747, 2012). "Similarly, although the expression of Cpt1a decreased in fasted PASK-deficient mice no hypoglycemia were observed after fasting (24 h or 48 h) in PASK-deficient mice." (PMID 30038292, 2018). "Given that those with loss of function variants in KCNQ1 may be prone to post-prandial hypoglycemia due to increased insulin release from the pancreas, increased vigilance is warranted when prescribing beta-blockers to those with both KCNQ1 variants and the CPT1A p.P479L variant." (PMID 38884101, 2024). "Thus, loss of CPT1a activity in the liver of CPT1a-deficient patients may cause the hypoketonemia, but not the hypoglycemia." (PMID 29898400, 2018). "In mice with inactivation of both Agpat5 and Cpt1a, hypoglycemia did not induce a significant reduction in glucagon secretion as compared to Agpat5flox/flox;Cpt1aflox/flox mice." (PMID 36180454, 2022).
glioblastoma (12 papers, 2015 to 2025). The most malignant astrocytic tumor (WHO grade IV). "Furthermore, high grade glioblastoma is associated with increased mRNA levels of both CPT1A and CPT1C." (PMID 25866768, 2015). "ST1326 represents a breakthrough as a brain-penetrant-selective CPT1A inhibitor designed for glioblastoma treatment." (PMID 40867868, 2025). "In glioblastoma multiforme, enhanced fatty acid metabolism by co-enhancement of CPT1A and CPT2 and immune checkpoint CD47, which functions as an anti-phagocytic signal, promotes the growth of radioresistant glioblastoma multiforme cells." (PMID 37601653, 2023). "Similar to our result of bioinformatics analysis, CPT1A is strongly expressed in HCC, but lower in glioblastoma." (PMID 34052835, 2021).
hyperlipidemia (12 papers, 2016 to 2025). "alkaloids (10–80 mg/kg, 8 days, PO) reduced hyperlipidemia by activating Acox1 and Cpt1a genes in mice fed with HFD." (PMID 37396948, 2023). "In contrast, the hypomethylation of the ATP-binding cassette transporter G1 (ABCG1) gene and hypermethylation of carnitine palmitoyltransferase 1A (CPT1A) have been correlated with postprandial lipemia." (PMID 37893238, 2023). "Genes related to the PPAR pathway and lipid peroxidation were significantly (P < 0.05) upregulated (PPARγ) or downregulated (PPARα, CPT1A, ACOX1) in the liver of hyperlipidemia group." (PMID 41144456, 2025). "In terms of lipid oxidative genes, including HMGCS2, CPT2 and CPT1A, no significant changes were observed, indicating that lipid oxidation might not be responsible for the increased lipid deposition in liver, at least not in the early stages of hyperglycaemia or hyperlipidemia induced NAFLD." (PMID 33186123, 2020).
non-alcoholic fatty liver disease (10 papers, 2019 to 2025). "NaB reduces the risk of non-alcoholic fatty liver disease (NAFLD) by inhibiting the mRNA levels of fatty acid synthase and increasing the mRNA levels of fatty acid oxidation-associated Cpt1a expression." (PMID 40791947, 2025). "Inhibition by miR-204 of the key enzyme in the carnitine-dependent transport pathway (cpt1a) in mouse hepatocytes promotes non-alcoholic fatty liver disease." (PMID 39591208, 2024). "miR204 is found to inhibit cpt1a in mouse hepatocytes, which could play a role in promoting non-alcoholic fatty liver disease." (PMID 36130994, 2022). "Similarly, the activation of liver AMPK, a well-known regulator of lipid metabolism and a direct upstream regulator of CPT1A, inhibited the accumulation of lipids in mouse liver and the development of nonalcoholic fatty liver disease (NAFLD)." (PMID 34680102, 2021). "Suppressing the activity of CPT1A during FAO has been found to inhibit the development of liver fibrosis and nonalcoholic fatty liver disease." (PMID 40606607, 2025). "For example, a decrease in CPT1a expression, coupled with enhanced long-chain acyl-CoA dehydrogenase (LCAD) and HADH mRNAs levels, was detected in liver biopsies from patients with non-alcoholic fatty liver disease." (PMID 34578953, 2021). "Despite the lack of direct evidence that GA upregulates FAO-related enzymes in the kidney, studies using a hepatocellular model of non-alcoholic fatty liver disease (NAFLD) have shown that GA increases the expression of FAO-related genes, such as PPARα and CPT1A, thereby reducing hepatic steatosis." (PMID 41170356, 2025).
acute myeloid leukemia (8 papers, 2021 to 2025). Acute myeloid leukemia (AML) is a group of neoplasms arising from precursor cells committed to the myeloid cell-line differentiation. "Cpt1a has been reported to be associated with genome-wide methylation in acute myeloid leukemia, alterations in acetyl-CoA levels, and H3K27ac at open chromatin sites in embryonic stem cells." (PMID 39786963, 2025). "Similarly, in acute myeloid leukemia (AML) and ovarian cancer, the overexpression of fatty acid-β-oxidation-related enzymes, such as CPT1A, has been associated with poor patient prognosis." (PMID 39759516, 2024). "In acute myeloid leukemia (AML), CPT1A inhibitors have shown significant anti-leukemia cell activity, and patients with lower expression levels have shown longer survival times." (PMID 39596847, 2024). "For instance, CPT1A overexpression has been shown to correlate with poor patient outcomes of acute myeloid leukemia (AML) and ovarian cancer." (PMID 35159223, 2022). "CPT1A is widely distributed in liver, pancreas, brain and blood, and it is also highly correlated with poor prognosis in acute myeloid leukemia (AML) or ovarian cancer." (PMID 36172157, 2022). "In acute myeloid leukemia (AML), overexpression of CPT1A indicates poor clinical prognosis, and strong synergistic inhibitory effects on AML were seen when the CPT1A-selective inhibitor ST1326 and the Bcl-2 inhibitor ABT199 were applied in combination." (PMID 37033619, 2023). "However, no systematic study was conducted to explore the prognostic value of CPT1a expression and possible treatment strategies with CPT1a inhibitor on acute myeloid leukemia (AML)." (PMID 33926484, 2021). "Studies have shown that the combination of ST1326 and ABT199 (Bcl-2 inhibitor) can enhance the anti-acute myeloid leukemia (AML) effect of the latter, indicating that cpt1a may become a potential drug target for the treatment of AML." (PMID 36588702, 2022).
breast tumor (8 papers, 2016 to 2024). "Restricting glucose availability reduced the proliferation of both Cpt1a-proficient and -deficient ErbB2+ breast tumor cells in a concentration-dependent manner." (PMID 39097623, 2024). "Genetic ablation of STAT3 in T cells or CPT1A inhibitor treatment in obese tumor-bearing mice suppresses breast tumor progression by reducing FAO, increasing glycolysis, and enhancing CD8+ T-cell functions." (PMID 39402302, 2024). "Five out of six primary breast tumour gene expression datasets analysed showed significantly lower CPT1A expression in ER-negative, compared to ER-positive tumours." (PMID 30092766, 2018). "Moreover, lung metastases compared to the corresponding primary 4T1 and EMT6.5 breast tumors displayed increased CPT1a expression." (PMID 36732635, 2023). "Analysis of The Cancer Genome Atlas (TCGA) databank showed that CPT1A mRNA level is significantly higher in Luminal B and HER2+ breast tumors." (PMID 27563814, 2016). "We observed that patients with metastatic breast cancer at diagnosis had higher CPT1A expression in their primary breast tumors compared to patients that did not develop metastases for at least 7 years." (PMID 36732635, 2023).
Hyperglycemia (8 papers, 2012 to 2025). An increased concentration of glucose in the blood. "Notably, the dysregulated genes Cpt1a, Foxo1 and Pdk4 also appeared in the network of top 10 upregulated and downregulated mRNAs, indicating that these mRNAs might associate with hyperglycemia and T2D in GK rats at the age of 3 and 4 weeks." (PMID 32095365, 2020). "Several carbohydrate metabolism genes involved in metabolism of monosaccharide and carbohydrate and hyperglycemia (e.g. CPT1A, GALK1, INS, LEPR, PRLR and SCD) are highly expressed in mouse CPE and only lowly in human CPE." (PMID 24391755, 2013). "In WT cells, hyperglycemia already triggered a reduction in CPT1A level and there was no further decrease in CPT1A in MIC26 KOs grown in hyperglycemia." (PMID 39393820, 2024).